LINC00869 (long intergenic non-protein coding RNA 869 )
Synonyms: FAM91A2
Gene: Long non-coding RNA gene on chromosome 1 (149,558,215 to 149,705,722, forward strand). Ensembl gene ENSG00000291158.
Gene Ontology:
Molecular function: pre-mRNA 5'-splice site binding; triplet codon-amino acid adaptor activity
Biological process: mRNA 5'-splice site recognition; translation
Cellular component: U1 snRNP
Diseases named in the same sentence as LINC00869 in open-access papers:
LINC00869 is named in the same sentence as 1 disease in open-access papers, as found by Europe PMC text mining. Sharing a sentence is not in itself a finding about the gene and the disease. The quoted sentences say what the papers report.
tumor (1 paper, 2021). "Notably, LINC00869 also possessed a significantly higher expression level in tumor tissues in comparison with non-tumor tissues (p = 4.964e−20), confirming the critical role of LINC00869 in the carcinogenesis of HCC." (PMID 34917132, 2021). "Owing to the fewer coexpression genes for LINC00869 in HCC tissues, we further compared the expression level of LINC00869 between the HCC tumor samples and non-tumor samples in GSE14520-GPL3921." (PMID 34917132, 2021).